CRP (C-reactive protein)
Diseases named in the same sentence as CRP in open-access papers (continued):
Sharing a sentence is not in itself a finding about the gene and the disease.
pneumonia (continued). "In this study, we also found that the adult pneumonia patients had higher leukocytes counts with lower lymphocyte differentials, and higher CRP and ESR values compared to the group without pneumonia." (PMID 22443897, 2012). "WBC did not add significantly to the CRB-65 score for both endpoints, CRP improved prediction of critical pneumonia (combined CRP + CRB-65 AUC = 0.81, p = 0.004), but not 30-day mortality (p = 0.49)." (PMID 22501026, 2012). "The derivation study showed that three pieces of information are necessary to rule out pneumonia in these patients; C-reactive protein (CRP) level, dyspnea (no/yes), and daily feeling of increased body temperature since onset of cough (no/yes)." (PMID 23245504, 2012). "In patients with C-reactive protein values below 10 μg/ml or patients presenting with C-reactive protein between 11 and 50 μg/ml, but without dyspnoea and daily fever, pneumonia can be ruled out." (PMID 21569472, 2011). "Elevated CRP levels have been demonstrated in HIV infected patients with confirmed tuberculosis and in patients with a clinical syndrome compatible with either pneumonia or tuberculosis." (PMID 21249220, 2011). "Epidemiological data from a pneumococcal vaccine trial conducted in South Africa, a country with virtually no malaria, suggested that PCT and CRP can contribute to increase pneumonia endpoint specificity resulting in an increase of measured efficacy." (PMID 20976241, 2010). "Unfortunately, CRP does not allow the possibility to distinguish between all the types of pneumonia." (PMID 20011658, 2009). "The severity of their pneumonia was much lower as reflected by a high number of patients with low CRB-65 scores and a significantly lower inflammatory response as reflected by median leukocyte counts and CRP values on admission." (PMID 19439072, 2009). "C-reactive protein, leukocyte count, and radiological diagnosis of early-onset pneumonia on day 3 were not statistically different between the groups." (PMID 18554414, 2008). "The current study thus indicates that the specificity of CXR-confirmed pneumonia for diagnosing pneumococcal pneumonia may also be improved in children with HIV through the concurrent use of procalcitonin and CRP." (PMID 15736995, 2005). "Although we are unaware of data to support that CRP and procalcitonin are elevated in those with severe pneumonia, the absence of such data supporting this interpretation does not rule out this possibility." (PMID 15736995, 2005). "In children not infected with HIV with CXR-confirmed pneumonia, procalcitonin and CRP values were available for 132 (78.1%) of 169 vaccine recipients and 167 (78.8%) of 212 placebo recipients (p = 0.88)." (PMID 15736995, 2005). "Results revealed that pneumonia (OR 4.904 [95% CI 3.410–6.397]), EVD (OR 5.883 [95% CI 4.513–7.253]), tracheotomy (OR 5.983 [95% CI 4.619–7.348]), PCT (OR 4.332 [95% CI 3.048–5.616]), CRP (OR 6.862 [95% CI 5.127–8.597]), and Alb (OR 4.679 [95% CI 3.610–5.747]) were independent risk factors." (PMID 40529435, 2025). "The longer recovery period for FN or pneumonia for the Japanese may be attributed to differences in the medical environment in Japan, such as the continuation of antibiotics until CRP-negative." (PMID 40815417, 2025). "Similarly, we quantified the incidence of concomitant postoperative infectious complications unrelated to the primary pathology, such as pneumonia or a UTI, which could impact the CRP level." (PMID 40363964, 2025). "Laboratory tests may show elevated white blood cell counts and C-reactive protein levels in patients with this disease, though not as significantly as in pneumonia." (PMID 40575565, 2025). "Although Betadine coating could not reduce peristomal wound infection or pneumonia, we did find a lower elevation of serum CRP level and N/L ratio after PEG implantation in the Betadine group." (PMID 37189057, 2023).
pneumonia (continued). "In addition to CRP, baseline GDF-15 and MMP-8 were also associated with future pneumonia risk independent of clinical comorbidities." (PMID 38105941, 2023). "Compared with ordinary pneumonia patients, patients in the severe group presented with significantly higher LDH, neutrophil count, high-sensitivity troponin T (HS-TnT), C-reactive protein (CRP), human serum amyloid A (SAA), N-terminal pro-brain natriuretic peptide (NTproBNP), and D-dimer." (PMID 37965268, 2023). "Three baseline serum protein measurements were associated with pneumonia risk independent of measured clinical factors: growth differentiation factor 15 (SHR 1.32; CI 1.02–1.69), C-reactive protein (SHR 1.16, CI 1.06–1.27) and matrix metallopeptidase 8 (SHR 1.14, CI 1.01–1.30)." (PMID 38105941, 2023). "A new serum biomarker panel including 2 proteins [C-reactive protein (CRP), lipopolysaccharide (LBP)] and 3 metabolites [Fasciculol C, PE (14:0/16:1(19Z)), PS (20:0/22:6(4Z, 7Z, 10Z, 13Z, 16Z, 19Z))] was developed to identify CAP and to distinguish severe pneumonia." (PMID 36859478, 2023). "For example, our study did not collect information on whether the patients had consumed alcohol or previously had pneumonia; furthermore, preoperative laboratory markers (e.g., C-reactive protein and erythrocyte sedimentation rate were not collected)." (PMID 36978138, 2023). "Second, the study only investigated the associations of blood cell counts and related indicators with pneumonia in cerebral hemorrhage patients, but did not investigate other inflammatory indicators including C-reactive protein, interleukin-6 and other inflammatory factors." (PMID 37904408, 2023). "In 11 out of 472 pneumonia cases, CRP could not be assessed due to insufficient volume for all assays." (PMID 36963048, 2023). "For people presenting with symptoms of lower respiratory tract infection in primary care, the NICE guideline recommends using the results of CRP to guide the prescription of antibiotics if a diagnosis of pneumonia has not been made, while all patients with CAP should be offered an antibiotic." (PMID 37876022, 2023). "In addition, MMP levels in pneumonia are positively correlated with CRP levels, but this correlation is not as clear in KD because MMP levels in patients with CALs are significantly higher than in non-CAL patients." (PMID 37575991, 2023). "Thus, our findings suggests that LUS is a useful tool for the diagnosis of acute pneumonia in CCU and is accuracy improved combining information from serum C reactive protein mainly reducing the number of false positive results and increasing the specificity of the test." (PMID 36553089, 2022). "However, the possibility of pneumonia should be considered in patients with advanced age, high CRP levels, and high viral loads even if they have negative initial chest CT findings." (PMID 35239734, 2022). "Subgroup analysis of a cluster-randomised trial in urban Tanzania found that management of pneumonia with an algorithm which included oximetry measurements and point of care testing of CRP enabled more patients to be managed without antibiotics and in the community, with an improvement in outcomes." (PMID 36040992, 2022). "However, in patients with AdV-infected pneumonia alone, immune-related indicators (total IgA, CRP, and LDH) were also not significantly different between the two groups." (PMID 35979256, 2022). "Therefore, in our cohort, CRP was not useful as an aid for the diagnosis of NEC or pneumonia, in the absence of bloodstream infection." (PMID 36517750, 2022). "Moreover, several meta-analyses have suggested that CRP performs no better than the pneumonia-specific scores in prognostic prediction." (PMID 35307030, 2022). "Clinical data, CRP- and Procalcitonin (PCT)-values were retrieved from a prospectively maintained database and evaluated for their predictive value for subsequent postoperative infectious complications (PIC) (AL, gastric conduit leakage or necrosis, pneumonia, empyema)." (PMID 36233522, 2022).
pneumonia (continued). "CRP in our cohort was raised but not as high compared to other pneumonia." (PMID 34244563, 2021). "Patients with COVID-19 pneumonia were older, had a higher BMI, more likely to have comorbidity, more likely to have symptom, such as fever, cough, dyspnea and desaturation, lymphocytopenia, higher C-reactive protein (CRP), lower albumin, and higher globulin than those without pneumonia." (PMID 33902480, 2021). "Moreover, since Groups 1 and 2 had more cases of mild pneumonia, and laboratory values for the poor prognosis (lymphocyte count, N/L ratio, LDH level, ferritin level, d dimer level, CRP) were better than the other groups, and the difference was statistically significant." (PMID 34418000, 2021). "Besides, the elevated expression of NNT-AS1 is proportionate to CRP and PCT in children with refractory pneumonia, and NNT-AS1 may distinguish these patients with high accuracy." (PMID 34558385, 2021). "We hypothesized that biomarkers would improve the clinical and radiological diagnosis of pneumonia, and assessed the accuracy of CRP, PCT, SAA, NP and the ratios CRP/NP and SAA/NP in the PneumOldCT study, a cohort of elderly patients with CT-scan confirmed pneumonia." (PMID 32997689, 2020). "Overall, 28% of the patients were considered not having pneumonia after CRP analysis." (PMID 33399009, 2020). "None of the physicians in our study shifted from ‘sure’ to ‘no pneumonia’ after CRP testing." (PMID 33399009, 2020). "In 28% of the cases, there was no longer any suspicion of pneumonia after CRP." (PMID 33399009, 2020). "In a corresponding analysis with ‘any suspicion of pneumonia’ or ‘no longer pneumonia’ after CRP testing, as dependent variables, CRP emerged as a predictor of any suspicion of pneumonia and abnormal chest sounds remained associated with any suspicion of pneumonia." (PMID 33399009, 2020). "However, in another study CRP level did not prove to be a reliable measure to ban pneumonia in primary care." (PMID 33399009, 2020). "However, CRP testing has a low validity for diagnosing pneumonia compared to a chest X-ray, and there is no agreement about where to set the cut-off point." (PMID 31650886, 2020). "However, because consistent evidence for the specificity of C-reactive protein and procalcitonin for the diagnosis of ‘clinically defined pneumonia’ is lacking, both parameters cannot currently be recommended as diagnostic criteria." (PMID 32071433, 2020). "The use of biomarkers including C-reactive protein might aid in this adjudication since this has been shown to significantly decrease duration of antimicrobials in both humans and dogs with pneumonia without negatively affecting outcome." (PMID 32258067, 2020). "Further CRP testing seems to be most valuable when the GP is not sure of the diagnosis and hence could contribute to exclude the diagnosis of pneumonia and thereby might keep the prescriptions of antibiotics restrictive and purposeful." (PMID 33399009, 2020). "In addition, patients with pneumonia were significantly longer mechanically ventilated than patients who did not develop pneumonia, and they had higher CRP levels during collection of the first sputum study sample." (PMID 31662033, 2019). "Moreover, in the studied episodes of hospital care diagnosed with pneumonia, the presence of a respiratory virus was associated neither with clinical outcomes, nor with WBC or CRP values." (PMID 30991957, 2019). "Similarly, 65% of definite bacterial pneumonia had elevated CRP (≥72 mg/L) and the absence of rhinorrhea, compared to 7% of presumed viral and other pneumonias, and 2% of presumed viral pneumonias." (PMID 30940126, 2019). "With better pretest (pre-chest X-ray) assessment, for example by using CRP, pneumonia could be ruled out more often without chest X-ray." (PMID 31455104, 2019).
pneumonia (continued). "Future research should also focus on the value that POC CRP potentially has in more correctly identifying the children in primary care that suffer from pneumonia, as current evidence shows no definite cut-off levels that are useful to rule in the child in need of antibiotic treatment." (PMID 30564733, 2018). "However, no studies have investigated the changes in temporal values of inflammatory markers in relation to the reference level of preoperative CRP in patients with no infectious complications of pneumonia, urinary tract infection, and PJI." (PMID 29854731, 2018). "In addition to being able to distinguish between cases with bacterial vs RSV pneumonia, the informative value of CRP in etiology studies includes its ability to distinguish between bacterial pneumonia cases and controls without pneumonia." (PMID 28575375, 2017). "Our study included pneumonia patients regardless of the degree of inflammation because we could not use C-reactive protein which is a marker of the inflammation despite we tried to adjust pneumonia severity by using A-DROP system." (PMID 29284447, 2017). "Additionally, among HIV-negative CXR+ cases, CRP ≥40 mg/L was more common among older children and those with very severe pneumonia, fever, or absence of wheeze (all P ≤ .001, adjusted for site and age)." (PMID 28575375, 2017). "Initial DNI, which was measured upon ED arrival, was significantly higher in the ADHF with pneumonia group than in the ADHF group, and the predictive ability of initial DNI for ADHF with superimposed pneumonia in the ED was better than those of serum WBC and CRP." (PMID 27682424, 2016). "However, approximately 50% with CXR-confirmed pneumonia in our study had CRP <80 mg/L and a viral pathogen detected by NPH-qPCR, suggesting that some of the CXR-confirmed pneumonias might only have been of viral origin." (PMID 26821179, 2016). "In our study 92% of all patients had an elevated CRP (>10 mg/L) within the first week, whether they developed pneumonia or not." (PMID 26937636, 2016). "Importantly, a 2004 update for guidelines of the British Thoracic Society (BTS) suggested that CRP should not be used as a marker for pneumonia severity since an elevation in CRP is not specific and has no direct correlation to the severity of pneumonia." (PMID 25821793, 2015). "Moreover, CRP combined with PCT has demonstrated value in predicting pneumonia in adults, but interest in pediatric populations as not been well demonstrated." (PMID 25927410, 2014). "On the other hand, CRP may increase in many diseases, especially in pneumonia, as it is a non-specific inflammatory marker." (PMID 23902711, 2013). "This difference in CRP was observed in patients with pneumonia but not in trauma patients." (PMID 24286072, 2013). "Pneumonia could be ruled out in patients with CRP levels below 50 μg/ml who lacked dyspnea and daily subjective feeling of increased body temperature since onset of cough." (PMID 23245504, 2012). "In the current study reported here, median C-reactive protein and procalcitonin levels on admission were significantly higher in children with confirmed bacterial pneumonia than in children with pneumonia without bacterial confirmation, but there was a degree of overlap (data not shown)." (PMID 21695128, 2011). "The aim of this study was the development of a diagnostic aid, based on clinical signs and the measurement of C-reactive protein, to support physicians to safely rule out pneumonia in patients with cough and fever and to help in reducing unnecessary prescriptions of antibiotics." (PMID 21569472, 2011). "Therefore, the CRP levels in patients with ALI/ARDS, including severe pneumonia, may be useful for distinguishing these cases from patients with CPE." (PMID 21696613, 2011).
pneumonia (continued). "The significant differences between the non-pneumonia and pneumonia pandemic influenza (H1N1) 2009 cases were the increased frequency of ICU care, the prolonged length of hospital stay, more disability following infection and a higher peak CRP level (reference range <5 mg/L)." (PMID 20877727, 2010). "Similarly, PCT and CRP did not demonstrate any value in predicting death among Malawian children with signs of pneumonia or meningitis." (PMID 20976241, 2010). "The distributions of C-reactive protein concentration and blood leukocyte count did not suggest major differences in proportions of episodes with bacterial aetiology in the different severity categories of pneumonia." (PMID 18644109, 2008). "This may also explain why some studies have found procalcitonin and CRP not to be useful in distinguishing between bacterial and “viral” pneumonia." (PMID 15736995, 2005). "Patients with atypical pneumonia were previously thought to have the following characteristics: typical patient history, lack of purulent sputum, typical chest X-ray findings, absence of leukocytosis, normal or moderately elevated C-reactive protein, and poor response to β-lactam therapy." (PMID 40630483, 2025). "Additionally, in the patients with influenza-associated pneumonia, the neutrophil percentage, hypersensitive C-reactive protein level, and lactate dehydrogenase level were significantly higher, while the level of protein was significantly lower, than those in patients without pneumonia." (PMID 35382755, 2022). "In the model development population, pneumonia patients (n = 227) had a longer duration of fever; higher frequencies of purulent sputum, dyspnea, and thoracic pain; and higher levels of respiration rates and C-reactive protein (CRP) than non-pneumonia patients (n = 500)." (PMID 36253753, 2022). "Predictive performance for pneumonia was analyzed in five selected blood parameters (percentage counts of neutrophils, lymphocytes, and eosinophils, percentages of hematocrit, and serum concentrations of CRP) that were significantly different between pneumonia and non-pneumonia patients." (PMID 36253753, 2022). "Pairwise between group comparisons showed that the FCBI-index and CRP values of the bacterial pneumonia subgroup were statistically significantly increased when compared with the six virally infected RTI subgroups and patients having pneumonia with unknown etiology." (PMID 34844193, 2021). "For people presenting with symptoms of lower respiratory tract infection in primary care, consider a point-of-care C-reactive protein test if after clinical assessment a diagnosis of pneumonia has not been made and it is not clear whether antibiotics should be prescribed." (PMID 33153517, 2020). "The combination of CRP (≥72 mg/L) with either the presence of fever or absence of rhinorrhea, improved the specificity and PPV for differentiating bacterial pneumonia from presumed viral plus other pneumonias compared to the CRP alone, with little loss of sensitivity and NPV." (PMID 30940126, 2019). "In study episodes diagnosed with pneumonia, the presence of a respiratory virus was neither associated with clinical outcomes (i.e. over 13-night hospital stay, number of revisits or death at ward) nor with WBC values over 15 × 109/L or CRP values over 100 mg/l (all P > .1)." (PMID 30991957, 2019). "C-reactive protein concentration (6.5 mg/dL vs. 2.6 mg/dL; p<0.001), leukocyte count (7.5 × 103 cells/μL vs. 6.5 × 103 cells/μL; p = 0.001), and neutrophil count (5.5 × 103 cells/μL vs. 4.3 × 103 cells/μL; p<0.001) were significantly higher in patients with pneumonia than in those without pneumonia." (PMID 30560776, 2019). "CRP concentrations in this population were highly elevated, even in the absence of HIV or self-reported malaria, pneumonia, or diarrhea, and considering inflammation associated with pregnancy, indicating that there may be other underlying causes of inflammation." (PMID 29986492, 2018).